DPP4 (dipeptidyl peptidase 4)
Diseases named in the same sentence as DPP4 in open-access papers (continued):
Sharing a sentence is not in itself a finding about the gene and the disease.
diabetes (continued). "However, there have been few studies comparing the effectiveness of biguanides and DPP-4 inhibitors with respect to diabetes-related complications and cardio-cerebrovascular events over the long term, as well as the costs associated." (PMID 39121166, 2024). "Therefore, it is essential for managing type 2 diabetes mellitus to identify DPP-4 inhibitor peptides from natural sources and subsequently develop biofunctional foods, reducing reliance on synthetic inhibitors." (PMID 38667785, 2024). "Both drugs prevented foot process effacement and attenuated urinary albumin excretion, thereby contributing to a deeper understanding of the renal protective mechanisms associated with sodium glucose cotransporter 2 (SGLT2) and dipeptidyl peptidase-4 (DPP4) inhibitors in diabetes." (PMID 39201721, 2024). "Out of the participants with diagnosed diabetes (n=33), 75.8% (n=25) were prescribed metformin, 15.2% (n=5) sulfonylurea, 3.03% (n=1) Dipeptidyl Peptidase 4 inhibitors (DPP-4), while 12.1% (n=4) reported to be taking Sodium-glucose Cotransporter-2 inhibitors (SGLT-2)." (PMID 38752177, 2024). "Analysis of clinical data has shown that glucose-lowering agents (GLP1 receptor agonists, SGLT2 inhibitors, metformin and DPP4 inhibitors) reduce the risk of dementia in patients with diabetes and that this neuroprotective effect is independent of weight loss." (PMID 36998046, 2023). "In contrast, STG is a commercial DPP4 inhibitor for diabetes." (PMID 36935456, 2023). "For example, there is evidence to suggest that the use of dipeptidyl peptidase-4 (DPP-4) inhibitors, a class of medications commonly prescribed for the management of diabetes, may be associated with an increased risk of BP." (PMID 38201366, 2023). "Public diabetes service attenders were more likely to use insulin treatment (71.1% vs. 41.3%, p = 0.001), dipeptidyl peptidase-4 inhibitors (DPP4i) (44.7% vs. 21.3%, p = 0.002), and glucagon-like peptide-1 receptor agonists (GLP-1 RA) (13.2% vs. 2.6%, p = 0.002)." (PMID 37152098, 2023). "It has also been observed that the incidence of PD in patients with T2D was significantly lower in those given GLP-1 receptor agonists or dipeptidyl peptidase 4 (DPP4) inhibitors compared with individuals prescribed any other oral combination therapy for diabetes." (PMID 36436068, 2023). "Recent studies have demonstrated that DPP4 inhibitors that directly target the liver could be effective in relieving IR, which could be a better and more effective strategy for treating diabetes." (PMID 36769291, 2023). "However, to confirm and expand upon these findings regarding the influence of DPP-4 inhibitors on T cells in patients with diabetes and CKD, large-scale, randomized prospective studies will be essential." (PMID 38065905, 2023). "DPP-4 inhibitors, known as Gliptins, are a class of oral anti-diabetes drugs." (PMID 37064327, 2023). "Interestingly, DPP4 has a striking role in these disorders, especially in type 2 diabetes mellitus (T2DM)." (PMID 37896834, 2023). "DPP-4 inhibitors could be promising repurposed drugs to minimize inflammatory pathogenesis and disease severity in COVID-19/diabetes comorbidity." (PMID 37064327, 2023). "Whether the increased levels of circulating Gal-4 found in this study are related to a decreased ability to transport DPP4 and thereby increasing the odds of diabetes is beyond the scope of this study." (PMID 37985679, 2023). "In addition to its role in diabetes, the biological role of DPP4 in various types of cancers, including HCC and ccRCC, has also been investigated." (PMID 36508088, 2023). "Of the 124,718 papers published in the field of diabetes in the last 10 years, 3890 (3%) were meta-analyses, with more than 100 on dipeptidyl peptidase-4 (DPP-4) inhibitors, glucagon-like peptide-1 (GLP-1) receptor agonists and/or sodium–glucose cotransporter 2 (SGLT-2) inhibitors." (PMID 36547691, 2023).
diabetes (continued). "The available oral drugs in clinical use for the treatment of diabetes include biguanides, sulfonylureas, insulin sensitizers, glinide insulin secretagogue, α-glucosidase inhibitors, dipeptidyl peptidase-IV (DPP-4) inhibitors, and sodium-glucose cotransporter 2 (SGLT-2) inhibitors." (PMID 37175187, 2023). "Dipeptidyl peptidase-4 inhibitors (DPP4is) and sodium glucose cotransporter-2 inhibitors (SGLT2is) have been speculated to have a potential to increase infection risks in type 2 diabetes mellitus (T2DM) patients." (PMID 37891260, 2023). "Regardless of the duration of diabetes being less than 3 years or 3 years or more, the use of DPP4 inhibitors was associated with a reduced risk of PD." (PMID 38110464, 2023). "This suggests that repurposing DPP-4 inhibitors could be effective for treating COVID-19 patients with diabetes." (PMID 37064327, 2023). "The level of DPP-4 in the sperm cells of diabetic males is much lower than that of healthy males, and DPP-4 inhibitors may impair fertility in males with diabetes." (PMID 37893048, 2023). "Their hypoglycemic mechanisms have also been clarified at some classic diabetes treatment targets, such as the insulin receptor signaling pathway or other related pathways involved in the progress of diabetes, and key enzymes including α-amylase, α-glucosidase, and dipeptidyl peptidase-IV (DPP-4)." (PMID 36904097, 2023). "Most promising are the three novel classes of mediations which have thus far been largely studied in adult patients: GLP1 receptor agonists, DPP4 inhibitors, and SGLT2 inhibitors, as well as dietary approaches to reverse diabetes and its associated complications (e.g., VLEDs)." (PMID 34913986, 2022). "Therefore, further prospective randomized clinical trials are needed to investigate the role of DPP4 inhibitors in patients with diabetes mellitus and COVID-19." (PMID 35456343, 2022). "Dipeptidyl peptidase-4 inhibitors (DPP-4is) have been developed as oral antidiabetic agents in type 2 diabetes mellitus (T2DM), as they prevent the degradation of incretins such as glucagon-like peptide 1 (GLP-1) and glucose-dependent insulinotropic polypeptide (GIP)." (PMID 35164839, 2022). "Therefore, DPP4 could be a probable link between COVID-19 and DM, which may clarify the susceptibility of diabetes patients to the effect of COVID-19." (PMID 36355535, 2022). "Interestingly, multiple analyses from independent retrospective observational studies reported significant improvement in severe outcomes and mortality among patients with COVID-19 and type 2 diabetes mellitus (T2DM) using a DPP4 inhibitor." (PMID 35195023, 2022). "Indeed, DPP4 inhibitors represent a class of antidiabetic agents widely used for the treatment of Type 2 diabetes mellitus (T2DM)." (PMID 36140405, 2022). "A study showed that DPP-4 inhibitors with good safety and low incidence of hypoglycemia could be a great choice for elderly type 2 diabete mellitus patients." (PMID 35966053, 2022). "Similarly, even though the therapeutic effects of dipeptidyl peptidase-4 (DPP-4) inhibitors on type 2 diabetes mellitus are understood, their effectiveness across sub-groups of age, ethnicities and renal function remains undefined." (PMID 35652294, 2022). "In patients with type 2 diabetes, kallikrein-related peptidase 5, an enzyme responsible for the shedding of DPP4 from cell membrane, was induced in CD4+ T cells, suggesting that immune cell-derived DPP4 is responsible for reduced incretin effect in diabetes patients." (PMID 35309368, 2022). "To observe the effect of diabetes on cognitive function and further investigate the potential effect of DPP-4 inhibitor on diabetic cognitive dysfunction, we built diabetic rat model (see Materials and Methods section) and evaluated the rats' learning and recognition ability by MWM test." (PMID 39280108, 2022). "COVID-19 may affect DPP4 in patients with diabetes mellitus, leading to high mortality of diabetes mellitus combined with COVID-19." (PMID 34996987, 2022).
diabetes (continued). "However, the effects of DPP4 inhibition on the immune response in patients with diabetes is a matter of debate." (PMID 35370750, 2022). "Therapeutic diabetes drugs, particularly DPP4 inhibitors and/or GLP-1 analogs, may beneficially alter the pathophysiology of PD, reduce the incidence of PD, and improve the functioning of PD patients." (PMID 35873830, 2022). "DPP4 is long known for treating diabetes as it metabolizes glucagon-like peptide-1." (PMID 34880449, 2022). "Dipeptidyl-peptidase-4 (DPP4) inhibitors are novel medicines for diabetes." (PMID 35884882, 2022). "Interestingly, DPP4 has a striking role in these disorders, especially on type 2 diabetes mellitus (T2DM)." (PMID 36009573, 2022). "Dipeptidyl peptidase 4 activity is correlated with the onset and severity of obesity and diabetes." (PMID 35630534, 2022). "Due to the breadth of actions carried out by DPP4 substrates, impaired sDPP4 levels and DPP4 activity have been reported in several dysmetabolic conditions, such as Type 2 diabetes mellitus (T2DM), obesity, metabolic syndrome, nonalcoholic fatty liver disease (NAFLD), and polycystic ovary syndrome." (PMID 36140405, 2022). "This study considers DPP4 as a promising therapeutic target for diabetes mellitus." (PMID 36014373, 2022). "Also, DPP4 activity is increased in diabetes, both type 1 and 2, and is negatively correlated with adiponectin levels." (PMID 35945358, 2022). "Similarly, we observed that diabetes-enhanced DPP4 expression in tissue and activity in plasma were closely related to diabetes-induced systemic inflammation and glucose intolerance." (PMID 35883204, 2022). "In recent years, DPP-4 inhibitors have been widely used to treat diabetes." (PMID 35615279, 2022). "In this context, we can conclude that our study has identified O. tenuiflorum compounds (1S-α-pinene, β-pinene, and dehydro-p-cymene) as the potential novel inhibitors for DPP4, highlighting the pharmacological significance of O. tenuiflorum against diabetes mellitus." (PMID 36014373, 2022). "Because of this, DPP4 inhibitor became a major target for the treatment of patients with diabetes." (PMID 34996987, 2022). "Interestingly the information about metformin targeting DPP-4 is scarce, and mostly points out co-treatment of a combination of DPP-4 inhibitors (gliptins) and metformin in diabetes and/or mild to moderate hypertension." (PMID 36046822, 2022). "Sitagliptin is a highly selective inhibitor of dipeptidyl peptidase-4 (DPP-4) and is used for the treatment of diabetes by inhibiting the activity of DPP-4 and prolonging the bioactivity of glucagon-like peptide −1 (GLP-1) and gastric inhibitory polypeptide (GIP)." (PMID 35635037, 2022). "The clinical use of DPP-4 inhibitors includes vildagliptin, Alogliptin, etc., which has a significant therapeutic effect on diabetes without increasing the risk of infection." (PMID 39280108, 2022). "Here, human proximal tubular epithelial cells (PTECs) were treated with normal glucose, high glucose, and anti-diabetes agents, including SGLT2i (dapagliflozin), metformin, and dipeptidyl peptidase-4 inhibitor (DPP-4i, vildagliptin) and microarray analysis was performed." (PMID 35129424, 2022). "DPP-4 inhibitors have therapeutic effects on diabetes-related cognitive dysfunction." (PMID 39280108, 2022). "Genetic ablation of Dpp4 in mice improves insulin sensitivity and liver glucose metabolism, and DPP4 pharmacological inhibition reduces the development of hepatic steatosis and insulin resistance in mouse models of obesity and diabetes." (PMID 35190847, 2022). "Teneligliptin, a dipeptidyl peptidase-4 inhibitor, is used to treat type 2 diabetes mellitus." (PMID 34512362, 2021). "Twenty participants (65%) were enrolled with pre-diabetes, 13 were diagnosed during screening for this study (12f: 1m); 3 of the 7 who were previously diagnosed were on glucose-lowering medication; all 3 on metformin, 1 in combination with a DPP-4 inhibitor." (PMID 34454636, 2021).
diabetes (continued). "We used a single injection and found out that the single injection of non-diabetic plasma could reverse M1/M2 cytokine expression, DPP4 activity, inflammatory cytokine expression of liver, and Kupffer cell activation in diabetes." (PMID 34043673, 2021). "The mice groups in this study were divided as follows: Cont, control (db/m mice); T2DM, type 2 diabetes mellitus mice (db/db mice); Vil.G, db/db + vildagliptin 50 mg/kg/day, positive control, dipeptidyl peptidase-4 (DPP-4) inhibitor; Bla.C, db/db + blackcurrant 200 mg/kg/day." (PMID 34836432, 2021). "Recent evidence has revealed that DPP-4 inhibitors such as saxagliptin and sitagliptin may exhibit a protective effect against the progression of renal injuries in diabetes." (PMID 34067150, 2021). "In line with our findings, DPP-4 inhibitors improve liver dysfunction in type 2 diabetes mellitus." (PMID 33889154, 2021). "In addition to its involvement in the development of diabetes, accumulating evidence indicates the role of DPP4 in IRI." (PMID 33928135, 2021). "Therefore, DPP4 inhibitors should better be avoided in diabetes patients with dementia and/or taking spironolactone." (PMID 33995274, 2021). "Subsequently, increased inflammatory cytokine expression and plasma DPP4 activity may promote insulin resistance and glucose intolerance in diabetes." (PMID 34043673, 2021). "Recent studies have reported that some anti-diabetes drugs may have beneficial effects in HF, including dipeptidyl peptidase-4 (DPP-4) inhibitors, glucagon-like peptide-1 receptor agonists (GLP-1 RAs), and SGLT-2 inhibitors." (PMID 34759887, 2021). "Ninety-five of 461 patients had a known history of diabetes (20.61%), with 56 (58.95%) patients on only insulin therapy, 25 (26.32%) on oral antidiabetic agents (including metformin, sulfonylureas and dipeptidyl peptidase 4-inhibitors), and 11 (11.58%) on a combination of insulin and orals." (PMID 33814982, 2021). "In addition to their role in treating diabetes, several studies have evaluated the potential of DPP-4 inhibitors as immune-modulating agents and as a treatment for chronic allograft dysfunction following lung transplantation." (PMID 35002970, 2021). "Dipeptidyl peptidase-4 inhibitors (DPP-4i), such as saxagliptin (Sax) and sitagliptin (Sit), are currently recommended by the American Association of Clinical Endocrinologists (AACE) as first-line hypoglycemic treatment in type 2 diabetes mellitus (T2DM)." (PMID 34123848, 2021). "DPP-4 inhibitors, widely used to treat type 2 diabetes mellitus, may be beneficial to COVID-19 patients with type 2 diabetes, as they can benefit from anti-inflammatory, anti-proliferative, and anti-fibrotic effects, in addition to glycemic regulation." (PMID 35822018, 2021). "However, we found that diabetes-induced plasma DPP4 activity and DPP4 expression in tissues were closely related with diabetes-induced systemic inflammation and glucose intolerance." (PMID 34043673, 2021). "In addition, several anti-diabetes drugs were evaluated in injured pancreatic islets and the effects of ile-pro-ile as a DPP4 inhibitor, and acarbose as an α-glucosidase inhibitor were confirmed." (PMID 34358068, 2021). "Because human DPP4 inhibitors are less efficient for bacterial DPP4, development of periodontopathic DPP4‐specific inhibitors and the usage for type 2 diabetes mellitus patients may synergistically reduce blood glucose concentration." (PMID 33006264, 2021). "Also known as gliptins, DPP4-inhibitors are a class of oral hypoglycemic drugs that antagonize the enzyme DPP4 and are generally used as a treatment for diabetes mellitus type 2 (DM-II)." (PMID 34298800, 2021). "A study has reported that treatment of diabetes with dipeptidyl peptidase-4 (DPP-4) inhibitors may increase pain in the joints." (PMID 34295586, 2021).
diabetes (continued). "Alkaloids, in recent years, have received extra attention due to their potential role in the treatment of diabetes through inhibition of α-glucosidase, α-amylase, dipeptidyl peptidase-4 (DPP-4), and AGEs and by possessing potent protein tyrosine phosphatase 1B (PTP1B) inhibitory effects." (PMID 34527069, 2021). "Although DPP4 is widely expressed in different cell types, its expression is much higher in adipocytes, fibroblasts and hepatocytes, especially in a variety of disease states including obesity and diabetes." (PMID 34926239, 2021). "Gliptins constitute a class of drugs increasingly used for the treatment of type 2 diabetes mellitus, inhibiting dipeptidyl peptidase 4 (DPP4), the enzyme that inactivates the incretin hormones such as glucagon-like peptide 1 (GLP1) and glucose dependent insulinotropic polypeptide (GIP)." (PMID 34577104, 2021). "Dipeptidyl peptidase-4 (DPP4) is a ubiquitous enzyme and is detectable in numerous tissues including endothelium, which degrades incretins such as glucagon-like peptide-1 (GLP-1) and causes diabetes in humans." (PMID 34531738, 2021). "DPP4 expression is dynamically regulated by a number of stimuli, and it has been reported that disease states including inflammation, chronic lung disease, cancer, obesity, and diabetes, can increase DPP4 expression in the lungs and other organs." (PMID 35059374, 2021). "Interestingly, we found that the differentially expressed protein DPP4 is also in figure, which is a protein closely related to diabetes." (PMID 34641785, 2021). "Inhibition of DPP-4 was also shown to ameliorate inflammation-induced bone resorption, and may therefore be useful not only for glycemic control in diabetes patients but also for treatment of inflammation-induced bone resorption." (PMID 34205264, 2021). "We are expecting more studies to validate the efficacy of DPP4-inhibitors in treating CRC patients or subgroups of CRC patients (such as those with diabetes comorbidity), and therefore, they can be promptly entered clinical application to improve the prognosis of CRC patients." (PMID 34298800, 2021). "In addition, two Japanese patients with hypoglycemia in infancy progressed to diabetes later in life due to the ABCC8 heterozygous inactivating variants and got better glucose control treated with DPP4 inhibitors." (PMID 34631896, 2021). "Moreover, further studies find that DPP‐4 is also involved in the cardiovascular complications of diabetes." (PMID 32713161, 2020). "DPP-4 inhibitors with anti-viral action may be more useful for infected patients with diabetes, while anti-coagulant treatment is proposed in severe SARS-CoV-2 induced pneumonia." (PMID 32485894, 2020). "Dipeptidyl peptidase-4 (DPP4) inhibitors are widely used for diabetes." (PMID 33050169, 2020). "DPP4 does cleave Ala containing dipeptides and thus lowering levels of His-Ala could result from higher levels of DPP4 in diabetes." (PMID 33381523, 2020). "Linagliptin is a DPP-4 inhibitor used for the treatment of type 2 diabetes mellitus." (PMID 33328991, 2020). "Eleftheriou et al25 suggested that DPP‐4 inhibitors might be beneficial to COVID‐19 infections with diabetes." (PMID 32713161, 2020). "In addition, concerning COVID-19 related vascular damage, it should be noted that, in contrast to preclinical evidence, human studies have shown either a neutral or a detrimental effect of DPP4 blockage on endothelial function in the setting of diabetes." (PMID 32456064, 2020). "An inhibitor of dipeptidyl-peptidase 4 (DPP-4), sitagliptin, is used in diabetes treatment." (PMID 33256016, 2020). "Furthermore, information about the effectiveness and safety of thiazolidinediones and dipeptidyl peptidase-4 (DPP-4) inhibitors for managing diabetes in patients with liver cirrhosis is insufficient." (PMID 33315940, 2020). "DPP4 inhibitors, or gliptins are approved for the treatment of type 2 diabetes mellitus." (PMID 33154981, 2020).